CNBP (CCHC-type zinc finger nucleic acid binding protein)
Diseases named in the same sentence as CNBP in open-access papers (continued):
Sharing a sentence is not in itself a finding about the gene and the disease.
tumor (continued). "Steady transfection of SMARCC2 led to decrease in volume, weight, proliferative index, microvessel density and M2 macrophage accumulation of subcutaneous tumours produced by IMR‐32 cells in immune‐deficient mice, and these effects were eliminated by transfection of CNBP." (PMID 37186134, 2023). "Interestingly, CNBP has been reported to be a key transcriptional regulator of tumor-promoting genes to control tumor cell biology." (PMID 36902726, 2023). "Besides, CNBP is also confirmed to act as a crucial regulator of cell biology by modulating oncogene expression in tumor." (PMID 35909906, 2022). "In addition, circHuR interacted with CNBP and subsequently restrained its binding to the HuR promoter, resulting in downregulation of HuR and repression of tumor progression." (PMID 35986300, 2022). "Consequently, the proliferation of tumor cells was greatly accelerated by CNBP overexpression, as determined by colony formation assay." (PMID 30335765, 2018). "Moreover, CNBP can act as a RBP that is involved in tumor progression." (PMID 38635778, 2024). "Together, these findings reveal the tumor-promoting effects of dietary fructose in CAC and highlight CNBP as a key regulator restraining Ereg expression." (PMID 41943842, 2026). "When circHuR interacts with CCHC-type zinc finger nucleic acid-binding protein (CNBP), it subsequently inhibits its binding to the HuR promoter, and at last down-regulates HuR and inhibits the progress of tumor." (PMID 34445958, 2021). "Mechanistically, circ-HuR interacted with CCHC-type zinc finger nucleic acid binding protein (CNBP), and subsequently restrained its binding to HuR promoter, resulting in down-regulation of HuR and repression of tumor progression." (PMID 31718709, 2019). "In addition, CNBP repressed the SMARCC2 activity to facilitate rRNA processing and ribosome biogenesis of tumour cells, leading to increase of M2 macrophage polarization." (PMID 37186134, 2023). "This work broadens current literature regarding the functions of SWI/SNF subunits in controlling ribosome biogenesis, and suggests that KPNB1/CNBP/SMARCC2 axis‐mediated ribosome biogenesis and M2 macrophage polarization is a valuable therapeutic target for tumours." (PMID 37186134, 2023). "Clinical NB cases with up‐regulation of KPNB1, CNBP, SMARCC1, SMARCA4 or down‐regulation of SMARCC2 have poor survival and prognosis, indicating KPNB1/CNBP/SMARCC2 axis as a valuable target for therapeutics of tumours." (PMID 37186134, 2023).
cancer (30 papers, 2013 to 2025). A tumor composed of atypical neoplastic, often pleomorphic cells that invade other tissues. "We then found that the most significant DEGs were tightly associated with progression of cancers, including PTMA, HNRNPR, RAPH1, TRAF3IP1, CNBP, and PRR15." (PMID 41347062, 2025). "By function assay, we found that circTADA2A exhibit its inhibitory effects in cancer progression via interacting with CNBP proteins to regulate SLC38A1 transcription." (PMID 38635778, 2024). "Together, these results suggest that CNBP may play an essential role in stress adaptation and cancer progression." (PMID 37425300, 2023). "To determine whether the role of CNBP is conserved in other cell types, we performed CNBP KO experiments in human Huh7.5 cells (a hepatocyte-derived cellular carcinoma cell line)." (PMID 37963251, 2023). "Since we had previously found that mammalian CNBP regulates polyamine metabolism by affecting translation of ODC in cancer cells, we asked if a similar mechanism could play a role in this context." (PMID 34517941, 2021). "We identify that circ-HuR is able to suppress the transcriptional activity of CNBP, and functions as an endogenous inhibitor for repressing the binding of CNBP to HuR promoter, resulting in down-regulation of HuR and its target genes involved in cancer progression." (PMID 31718709, 2019). "Translation of 5′-TOP motif-containing mRNAs is activated during cancer cell invasion, migration and metastasis, with RNA-binding proteins such as LARP1, CNBP, AUF1 and TIAR1 involved in this process." (PMID 40855114, 2025). "CNBP was shown to control transcription of c-MYC and KRAS oncogenes in human cancer by unfolding DNA G-quadruplex structures." (PMID 38635778, 2024). "In total, 31 genes were overlapped in both datasets and 12 genes (i.e., CNBP, HDAC2, LDAH, RPL6 and EIF4G2) were annotated in Cancer Gene Census or CancerMine38,39." (PMID 36681772, 2023). "Given the involvement of LARP1, CNBP, AUF1 and TIAR1 in 5′-TOP mRNA regulation and the largely unexplored nature of their regulatory networks, it is plausible that Ephexin1 coordinates with these proteins to modulate the translation of cancer-specific mRNAs." (PMID 40855114, 2025). "Also, many targeted genes, such as ZEB1, SOX5, AKAP1, CHP1, CNBP, VEGFR, and MAGT1, play a vital function in the cell shape, movement, invasion, adhesion, and polarity formation, so as to involve in many kinds of diseases such as malignant tumors, wound healing, and so on." (PMID 32547593, 2020). "One protein that showed upregulation at the protein level with no corresponding change in transcripts is CCHC-type Zinc finger Nucleic acid Binding Protein (CNBP), known to promote proliferation and chemoresistance in cancer." (PMID 37425300, 2023).
infection (10 papers, 2010 to 2026). The state of being infected such as from the introduction of a foreign agent such as serum, vaccine, antigenic substance or organism. "Here, we defined the contribution of CNBP in cytokine-driven immunity to Plasmodium infection including both P." (PMID 42282833, 2026). "Further work showed CNBP - a human cell protein that is elevated on infection and binds to SARS-CoV-2 genome - binds and unfold G4s from the SARS-CoV-2 genome in vitro." (PMID 37006620, 2023). "Abrogation of CNBP expression in humans cells led to increased SARS-CoV-2 RNA levels following infection." (PMID 37606964, 2023). "Paradoxically, the absence of CNBP delayed mortality in a lethal infection model and reduced inflammatory responses that are associated with cytokine storm-mediated immunopathology." (PMID 42282833, 2026). "Consequently, cells and animals lacking CNBP have higher viral loads and CNBP-deficient mice succumb rapidly to infection." (PMID 35547851, 2022). "Paradoxically, mice lacking CNBP in hematopoietic cells showed delayed mortality in the lethal infection model, underscoring its context-dependent contributions to host protection and inflammatory pathology." (PMID 42282833, 2026). "The CNBP-M was just as effective as the WT in blocking infection, suggesting that CNBP still inhibits SARS-CoV-2 infection independent of its role as a signaling molecule controlling type I IFN gene expression." (PMID 37963251, 2023).
genetic disease (2 papers, 2022 to 2024). "Myotonic Dystrophies type 1 and type 2 are complex genetic diseases caused by unstable CTG expansions (from 37 to up to several thousand repeats) in the 3′UTR of the DMPK gene (DM1) and CCTG expansions in the first intron of the CNBP (also known as ZNF9) gene (DM2)." (PMID 36142405, 2022). "Since both DM1 and DM2 are genetic diseases, the diagnosis of DM can be made by genetic testing, addressing the presence of CTG or CCTG repeats in the DMPK or CNBP genes using blood samples." (PMID 36142405, 2022).
CNBP also shares sentences with these, for which no sentence is quoted: Insulin resistance (15 papers); Hepatic steatosis (12); Obesity (6); prostate carcinoma (6); steatosis (5); atherosclerosis (4); dyslipidemia (4); Hypercholesterolemia (4); non-alcoholic fatty liver disease (4); autosomal dominant disease (3); spinocerebellar ataxia type 10 (3); Arrhythmia (2); diabetes mellitus type 2 (2); Huntington disease (2); Hyperinsulinemia (2); nonalcoholic steatohepatitis (2); ZIKV infection (2); Alzheimer disease (1); amyotrophic lateral sclerosis (1); arteriosclerosis (1); autism (1); benign adult familial myoclonic epilepsy (1); cardiac arrhythmia (1); cardiomyopathy (1); cardiovascular diseases (1); cholelithiasis (1); cholestasis (1); chronic kidney disease (1); clear cell renal cell carcinoma (1); Cognitive impairment (1).
A further 45 diseases each share a sentence with CNBP in 1 paper.